ZNF713 (zinc finger protein 713)
Description:
May be involved in transcriptional regulation.
Synonyms: FLJ39963
Tractability: PROTAC: ubiquitination databases record sites on it.
Gene: Protein-coding gene on chromosome 7 (55,887,456 to 55,942,530, forward strand). Ensembl gene ENSG00000178665.
Subcellular location: Nucleus
Subcellular location (Human Protein Atlas): Nucleoli
Pathways (Reactome):
Gene expression (Transcription): Generic Transcription Pathway
Gene Ontology:
Molecular function: sequence-specific double-stranded DNA binding; DNA-binding transcription factor activity, RNA polymerase II-specific; RNA polymerase II cis-regulatory region sequence-specific DNA binding
Biological process: regulation of DNA-templated transcription; regulation of transcription by RNA polymerase II
Cellular component: nucleus
Genetic constraint (gnomAD): Loss-of-function variants: 28 observed, 37.79 expected, observed/expected ratio (o/e) 0.74, 90% interval 0.55 to 1.02. The upper end of that interval is the gene's LOEUF score, 1.02, which puts it in group 4 of 6, group 1 being the genes least tolerant of losing a copy. Missense variants: 449 observed, 553.76 expected, observed/expected ratio (o/e) 0.81, 90% interval 0.75 to 0.88. Synonymous variants: 167 observed, 186.44 expected, observed/expected ratio (o/e) 0.9, 90% interval 0.79 to 1.02.
Homologues: Orthologues: chimpanzee ZNF713 (99% identical), chimpanzee ZNF713 (93% identical), pig ZNF713 (86% identical), rabbit ZNF713 (77% identical), mouse A430033K04Rik (35% identical). Paralogues in human: ZNF7 (46% identical), ZNF658 (45% identical), ZNF606 (45% identical), ZNF724 (45% identical), ZNF726 (45% identical), ZNF33B (44% identical), ZNF708 (44% identical), ZNF254 (44% identical), ZNF429 (44% identical), ZNF879 (44% identical), ZNF471 (43% identical), ZNF546 (43% identical), and 164 more.
Diseases named in the same sentence as ZNF713 in open-access papers:
ZNF713 is named in the same sentence as 6 diseases in open-access papers, as found by Europe PMC text mining. Sharing a sentence is not in itself a finding about the gene and the disease. The quoted sentences say what the papers report.
autism spectrum disorder (1 paper, 2024). A spectrum of developmental disorders that includes autism, and Asperger syndrome. "Previous research has identified a CGG repeat expansion mutation in the 5' intron region of the ZNF713 gene in some patients with neurodevelopmental disorders, potentially altering gene expression and function, and being associated with Autism Spectrum Disorder (ASD)." (PMID 40226717, 2024).
depression (1 paper, 2024). "The discovery and validation of TRPV2, ZNF713, and CTSL as potential biomarkers offer a promising avenue for enhancing the precision of depression diagnosis and advancing our understanding of this complex disorder." (PMID 40226717, 2024). "Although the potential roles of ZNF713 in neurodevelopmental disorders and immune responses are of interest, no studies have reported the relationship between ZNF713 and depression." (PMID 40226717, 2024).
neurodevelopmental disorder (1 paper, 2024). A behavioral and cognitive disorder with onset during the developmental period that involves impaired or aberrant development of intellectual, motor, or social functions. "ZNF713 is a protein with C2H2 zinc finger domains that plays a role in regulating gene transcription and has been linked to neurodevelopmental disorders." (PMID 40226717, 2024).
tumour (1 paper, 2010). "Eight genes centromeric to SEPT14 (ZNF713, MRPS17, GBAS, PSPH, CCT6A, SUMF2, PHKG1 and CHCHD2) were amplified in tumour 4 only." (PMID 21170331, 2010).
ZNF713 also shares sentences with these, for which no sentence is quoted: amyotrophic lateral sclerosis (1 paper); schizophrenia (1).